RN7SL420P (RNA, 7SL, cytoplasmic 420, pseudogene)
Gene: Miscellaneous RNA gene on chromosome 1 (115,606,471 to 115,606,768, forward strand). Ensembl gene ENSG00000239984.
Homologues: Orthologues: chimpanzee Metazoa_SRP (97% identical), rabbit Metazoa_SRP (60% identical). Paralogues in human: RN7SL1 (74% identical), RN7SL2 (73% identical), RN7SL3 (73% identical), RN7SL122P (72% identical), RN7SL296P (72% identical), RN7SL5P (71% identical), RN7SL441P (71% identical), RN7SL199P (70% identical), RN7SL408P (70% identical), RN7SL656P (70% identical), Metazoa_SRP (70% identical), RN7SL220P (70% identical), and 701 more.